PCSK9 (proprotein convertase subtilisin/kexin type 9)
Diseases named in the same sentence as PCSK9 in open-access papers (continued):
Sharing a sentence is not in itself a finding about the gene and the disease.
Hypercholesterolemia (continued). "Accordingly, PCSK9 inhibitors (PCSK9i) have proven to be an effective therapeutic approach for the treatment of hypercholesterolemia." (PMID 34440277, 2021). "Consistently, they reported that knockout of hepatic Surf4 using CRISPR-Cas9 significantly reduced plasma levels of cholesterol and TGs and reduced the development of atherosclerosis in a mouse model of hypercholesterolemia induced by overexpressing PCSK9." (PMID 34118252, 2021). "In an atherosclerotic ApoE−/− background or PCSK9 overexpression, Dscr-1 null mice revealed significant hypercholesterolemia leading to lipid accumulation in the peripheral tissues." (PMID 33895138, 2021). "The effects of GOF PCSK9, which results in sustained hypercholesterolemia and increased atherosclerotic lesions in mice in vivo, are consistently more pronounced than the effects of WT PCSK9 in our study." (PMID 33643060, 2021). "Proprotein convertase subtilisin/kexin type 9 (PCSK9) is of particular importance in cholesterol metabolism with high levels contributing to hypercholesterolemia." (PMID 33461570, 2021). "A novel mouse model of hypercholesterolemia was developed based on the mechanisms of action of pro-protein convertase subtilisin/kexin type 9 (PCSK9)." (PMID 34631822, 2021). "The aim of the studies was to evaluate the safety, tolerability, and efficacy of tafolecimab, a novel proprotein convertase subtilisin/kexin type 9 (PCSK9) monoclonal antibody, in Chinese healthy volunteers and patients with hypercholesterolemia." (PMID 36341216, 2021). "Actually, new gene-editing technologies are becoming promising tools for future therapeutic applications, also in the management of hypercholesterolemia by targeting PCSK9." (PMID 34070931, 2021). "Taken together, these results suggest that NPxY motif mutation in LRP1 abrogates cholesterol-induced LXR activation, thereby decreasing PCSK9 expression to suppress cholesterol-induced hypercholesterolemia." (PMID 33500241, 2021). "However, despite the addition of LDLRAP1 and PCSK9 to the list of genes that are associated with inherited hypercholesterolemia, there still appears to be a substantial number of patients with a clinical diagnosis of possible or defined FH who exhibit unknown genetic defect." (PMID 33807407, 2021). "At present, there is no concrete information on the inflammatory and coagulation status of the PCSK9-AAV mouse model of hypercholesterolemia." (PMID 34631822, 2021). "In the past decade, proprotein convertase subtilisin/kexin type 9 (PCSK9) emerged as a novel target for the treatment of hypercholesterolemia with the approval of 2 monoclonal antibodies, alirocumab and evolocumab." (PMID 36341216, 2021). "The data demonstrate that h5E12-L230G has the potential to serve as a therapeutic antibody targeting PCSK9 for treating hypercholesterolemia and relevant cardiovascular diseases." (PMID 34944600, 2021). "Cost-effectiveness of PCSK9 inhibitor therapy in patients with heterozygous familial hypercholesterolemia or atherosclerotic cardiovascular disease." (PMID 34709306, 2021). "The study on influence of anti-PCSK9 monoclonal antibody (mAb) treatment on platelets from subjects affected by familial hypercholesterolemia was first carried out in our laboratory." (PMID 34070931, 2021). "Initiation of PCSK9 inhibition in patients with heterozygous familial hypercholesterolemia entering adulthood: a new design for living with a high-risk condition?" (PMID 34709306, 2021).
Hypercholesterolemia (continued). "In asymptomatic patients with familial hypercholesterolemia, serum PCSK9 concentrations were independently predictive of coronary artery calcification (CAC)." (PMID 34199468, 2021). "PCSK9 inhibitors, monoclonal antibodies that bind to free PCSK9, have potent effect on LDL-C reduction, and are recommended to use in patients with high CVD risk or familial hypercholesterolemia." (PMID 33610176, 2021). "AS can result from familial hypercholesterolemia that is established following genetic defects in PCSK-9." (PMID 34860135, 2021). "The literature review we conducted reveals the limited use of proprotein convertase subtilisin/kexin type 9-inhibitors (PCSK9i) in children with familial hypercholesterolemia (FH)." (PMID 34692794, 2021). "Presently, both PCSK9 inhibitors have received approval for monotherapy use, for homozygous familial hypercholesterolemia (HoFH), and for secondary prevention of CV events." (PMID 34869702, 2021). "The previously-mentioned angiopoietin-like protein-3 (ANGPTL3) inhibitors (evinacumab) recently introduced in familial hypercholesterolemia follow the same development route as PCSK9 modulators." (PMID 34199468, 2021). "Rationale: Familial hypercholesterolemia (FH) is caused by mutations in genes involved in low-density lipoprotein cholesterol (LDL-C) metabolism, including those for pro-protein convertase subtilisin/kexin type 9 (PCSK-9)." (PMID 34944757, 2021). "In recent years, studies on familial hypercholesterolemia have focused on low-density lipoprotein receptor, apolipoprotein B and proprotein convertase subtilisin/kexin type 9 (PCSK9)." (PMID 34926596, 2021). "It has been recently shown that in primary hypercholesterolemia the in vivo treatment with PCSK9 inhibitors, beyond their lipid-lowering action, had important inhibitory effects on platelet aggregation and activation." (PMID 31963572, 2020). "It would be reassuring to find similar results with for example statin therapy in primary prevention setting, statin therapy in patients with diabetes mellitus, or PCSK9 inhibition in patients with familiar hypercholesterolemia." (PMID 32318625, 2020). "Since hypercholesterolemia is still one of the main risk factors for cardiovascular disease (CVD) and CVD mortality, PCSK9 evolved as a new target in the treatment of hypercholesterolemia." (PMID 33169229, 2020).
Hypercholesterolemia (continued). "PCSK9 have been approved for the treatment of hypercholesterolemia and for the secondary prevention of cardiovascular events." (PMID 32375792, 2020). "PCSK9 overexpression causes loss of hepatic LDL receptor surface expression and leads to hypercholesterolemia." (PMID 32949971, 2020). "Recent data showed that in patients with familiar hypercholesterolemia anti-PCSK9 mAb treatment inhibits platelet reactivity but it is unclear if this effect is mediated by a direct interaction between PCSK9 and platelets or by LDL lowering." (PMID 32252393, 2020). "Given that PCSK9 inhibitors are an efficacious second‐line drug class for the treatment of primary hypercholesterolemia and mixed dyslipidemia, we present these suggestive findings cautiously." (PMID 31714636, 2020). "Most importantly, PCSK9 overexpression induced hypercholesterolemia, as detected 4 weeks after PCSK9 injection (total cholesterol ~1800 mg/dl)." (PMID 32949971, 2020). "PCSK9 inhibitors have been developed primarily as an alternative therapeutic approach to treat hypercholesterolemia." (PMID 32644974, 2020). "It was found that individuals with PCSK9- LOF (loss of function) variants had lower levels of LDL-C; therefore, PCSK9 inhibition was proposed as a possible therapeutic approach to hypercholesterolemia." (PMID 32403394, 2020). "In the clinical context of hypercholesterolemia and PCSK9 treatment, it is clear that most patients will benefit from reducing PCSK9 levels because under such conditions, the level of PCSK9 is far too high." (PMID 33364976, 2020). "PCSK9 is mainly known as a molecule negatively affecting lipid metabolism, leading to hypercholesterolemia and consequent atherosclerotic plaque formation." (PMID 32225075, 2020). "The most likely explanation for correlations between hypercholesterolemia and AD is that hepatic expression of PCSK9 and subsequently of receptors such as VLDL and LDL-related protein-1 (LRP-1) is affecting the brain in a more indirect way." (PMID 33364976, 2020). "To circumvent genetic mouse models of atherosclerosis, we used a single intravenous injection of a well-characterized gain-of-function (D377Y) mouse PCSK9-AAV followed by WD feeding to induce rapid hypercholesterolemia to drive atherogenesis for 12 weeks." (PMID 32978273, 2020). "Irrespective of chronic inflammation, renal expression and secretion of PCSK9 in circulation is further induced by local and tissue-specific damage, such as podocyte damage induced by factors from nephrotoxic serum or hypercholesterolemia." (PMID 33364976, 2020). "Proprotein convertase subtilisin/kexin type 9 (PCSK9) has long been studied in the liver due to its regulation of plasma low-density lipoprotein cholesterol (LDL-C) and its causal role in familial hypercholesterolemia." (PMID 32595449, 2020). "In recent years, genetic studies recognized the critical role of proprotein convertase subtilisin/kexin type 9 (PCSK9) in cholesterol homeostasis and its direct association with familial hypercholesterolemia and hypocholesterolemia." (PMID 32824248, 2020). "The European Society of Cardiology/ European Society for Atherosclerosis released in 2017 a practical guideline for the use of PCSK9 inhibitors in patients with atherosclerotic cardiovascular disease or familial hypercholesterolemia." (PMID 32375792, 2020). "Recent studies have shown that an increased level of PCSK9 is a marker of the presence and severity of atherosclerosis in coronary and peripheral arteries in patients with heterozygous familial hypercholesterolemia." (PMID 33076542, 2020).
Hypercholesterolemia (continued). "The proprotein convertase subtilisin/kexin-9 (PCSK9) inhibitors evolocumab and alirocumab have emerged as a promising therapy for the treatment of hypercholesterolemia, since these agents are able to lower LDL-C by 50– 65%." (PMID 31969932, 2020). "Monoclonal antibodies against PCSK9 have shown potential in clinical trials for familiar hypercholesterolemia and cardiovascular diseases." (PMID 31296846, 2019). "The model was next used to predict the effects of the siRNA-mediated inhibition of PCSK9 synthesis, upon administration of inclisiran, in hypercholesterolemia subjects on statin treatment." (PMID 31292220, 2019). "In this retrospective study we investigated patients who were treated with PCSK9 inhibitors either because of intolerance of statins or residual hypercholesterolaemia with evidence of cardiac allograft vasculopathy." (PMID 30650126, 2019). "Two previous in silico studies have predicted the potential ability of T9 to inhibit two key targets in hypercholesterolemia treatment, such as PCSK9 and HMGCoAR." (PMID 31330826, 2019). "The reason for PCSK-9 inhibitor therapy (Evolocumab: 140 mg every two weeks n = 8; Alirocumab: 75 mg every two weeks n = 2) was statin intolerance (n = 6) or residual hypercholesterolaemia despite statin therapy (n = 4)." (PMID 30650126, 2019). "These genetic variants of PCSK9 affect both the plasma concentrations of PCSK9 and the serum level of LDL-C, thus becoming new targets for the treatment of hypercholesterolemia." (PMID 31915710, 2019). "Here, we describe a mouse model with liver-specific expression of human PCSK9 and a human-like hypercholesterolemia phenotype on chow diet." (PMID 30646909, 2019). "Together, these data demonstrate a clear PCSK9-driven hypercholesterolemic phenotype that worsens with age, similar to the lipid profile seen in humans with hypercholesterolemia." (PMID 30646909, 2019). "Since the discovery of proprotein convertase subtilisin/kexin type 9 (PCSK9) as an attractive target in the treatment of hypercholesterolemia, multiple anti-PCSK9 therapeutic modalities have been pursued in drug development." (PMID 31292220, 2019). "We made a dedicated effort because of the vital importance of PCSK9 in hypercholesterolemia and heart disease." (PMID 31805108, 2019). "In a more recent study, researchers generated a knock-in (KI) mouse with liver-specific expression of human PCSK9 driven by albumin promoter, termed hPCSK9-KI, to model of human hypercholesterolemia." (PMID 31117296, 2019). "Recent studies demonstrated that monoclonal antibodies neutralized the PCSK9 protein can reduce the plasma cholesterol in patients with hypercholesterolemia." (PMID 30704067, 2019). "Results show a hypercholesterolemic phenotype driven by PCSK9 that gets worse with age, similar to what has been seen in human hypercholesterolemia." (PMID 31117296, 2019). "To obtain a permanent model of hypercholesterolemia, we generated a knock-in (KI) mouse with liver-specific expression of human PCSK9, here termed hPCSK9-KI." (PMID 30646909, 2019). "In light of these observations, PCSK9 is currently considered a new target for the treatment of hypercholesterolemia, and the development of novel PCSK9 inhibitors is certainly a challenging goal." (PMID 31330826, 2019).
Hypercholesterolemia (continued). "When PCSK9 is dysregulated, such as through gain-of-function mutations in the PCSK9 gene, the protein impairs low-density lipoprotein (LDL)-cholesterol clearance by acting as an antagonist to the LDL receptor, thereby promoting hypercholesterolemia." (PMID 31762718, 2019). "Numerous approaches to inhibit PCSK9 have been developed for the treatment of hypercholesterolemia, including anti-PCSK9 monoclonal antibodies, small peptide inhibitors of PCSK926,27, and small interfering RNA28,29." (PMID 31332258, 2019). "Monoclonal PCSK9 antibodies are already on the market and small interfering RNAs studied as potentially effective drugs against hypercholesterolemia." (PMID 31114503, 2019). "Conversely, gain-of-function variants for PCSK9 result in high LDL-C levels and have been associated with familial hypercholesterolemia." (PMID 30899674, 2019). "Genetic defects in PCSK-9 lead to the establishment of familial hypercholesterolemia which ultimately progresses into AS." (PMID 31281844, 2019). "Herbal medicines are widely used for the treatment of hypercholesterolemia, and some natural products have been reported to regulate the transcription and expression of PCSK9 because of their cholesterol-lowering effects." (PMID 30235833, 2018). "Pharmacological intervention using statins and PCSK9 inhibitors have become first-line therapy in the prevention of hypercholesterolemia and atherosclerosis." (PMID 30115989, 2018). "This study is expected to be used as a preliminary screening method to further discover new drug candidates and provide a new perspective for the treatment of PCSK9-mediated hypercholesterolemia." (PMID 30235833, 2018). "As a result, PCSK9 emerged as a promising therapeutic strategy for the treatment of hypercholesterolemia and atherosclerosis." (PMID 30344267, 2018). "Familial hypercholesterolemia is an autosomal dominant inherited lipid disorder with LDL, apo-B, and PCSK9 mutations that results in persistent LDL elevation and early cardiovascular events." (PMID 30009049, 2018). "PCSK9 has been recently discovered as the third gene involved in the autosomal dominant form of hypercholesterolemia." (PMID 29230236, 2017). "For example, silencing messenger RNA (mRNA of PCSK9) is a new alternative against hypercholesterolemia." (PMID 29209441, 2017). "Inhibitors of another members of this gene family, PCSK9, show great promise as a new therapeutic intervention to control hypercholesterolemia and promote cardiovascular health in humans." (PMID 28814270, 2017). "FH management is mainly based on reducing plasma LDL-Cholesterol, and based on this logic a PCSK9 inhibitor can be used as a new therapy for hypercholesterolemia." (PMID 29230236, 2017). "In the third meta-analysis of 17 randomized controlled trials including 13,000 patients with primary hypercholesterolemia receiving PCSK9 inhibitors recorded a reduction of LDL-C level by 57%, total cholesterol by 46%, apo B by 53%, and PSCK9 by 59%." (PMID 29209441, 2017). "PCSK9 inhibitors are a new class of drugs that bring great hope for the treatment of hypercholesterolemia." (PMID 29209441, 2017).